PLA2G2A (phospholipase A2 group IIA)
Diseases named in the same sentence as PLA2G2A in open-access papers (continued):
Sharing a sentence is not in itself a finding about the gene and the disease.
allergic reaction (1 paper, 2022). "Therefore, we examined the impact of Pla2g2a deficiency on passive cutaneous anaphylaxis (PCA), an immediate-type allergic reaction that depends on mast cell degranulation." (PMID 35448539, 2022).
alopecia (1 paper, 2023). Hair loss usually from the scalp. "Mice transgenically overexpressing human sPLA2-IIA (PLA2G2A-TG) or sPLA2-X (PLA2G10-TG) show striking skin abnormalities characterized by epidermal thickening, sebaceous gland hyperplasia, and alopecia, independently of inflammation." (PMID 37189415, 2023).
cholangiocarcinoma (1 paper, 2024). A carcinoma that arises from the intrahepatic biliary tree (intrahepatic cholangiocarcinoma) or from the junction, or adjacent to the junction, of the right and left hepatic ducts (hilar cholangiocarcinoma). "Further validation is needed to understand the biological function of PLA2G2A in cholangiocarcinoma cells." (PMID 39267107, 2024). "STUB1 actively participates in the regulation of PLA2G2A transcription through these PTMs and influences the progression of cholangiocarcinoma." (PMID 39267107, 2024).
chronic cholecystitis (1 paper, 2022). "In such a way, PLA2G2A potentially wires long-term chronic cholecystitis up to GBC." (PMID 36198671, 2022).
chronic hepatitis B (1 paper, 2017). "The difference in serum levels of PLA2G2A was analyzed among chronic hepatitis B (CHB), LC, and HCC patients." (PMID 28077172, 2017).
colorectal tumor (1 paper, 2024). "Furthermore, PLA2G2A has been shown to impede colorectal tumor growth in mice." (PMID 39267107, 2024).
cyst (1 paper, 2018). A sac-like closed membranous structure that may be empty or contain fluid or amorphous material. "As in the case of transgenic mice overexpressing sPLA2-IIF, those overexpressing human sPLA2-IIA or sPLA2-X (PLA2G2A-TG and PLA2G10-TG, respectively) also develop alopecia and epidermal hyperplasia, accompanied by cyst formation, sebaceous gland hyperplasia, and a disturbed hair stem cell fate." (PMID 30546811, 2018).
diabetic foot ulcer (1 paper, 2025). "Fig7B and 7C displays the expression levels of CCL20, CXCL13, FGFR2, FGFR3, PI3, PLA2G2A, and S100A8 across the six cell types.The results showed that the key pathogenic genes of diabetic foot ulcer were mainly involved in keratinocytes and neutrophils." (PMID 40749079, 2025).
Down syndrome (1 paper, 2020). "Furthermore, this leads us to think about what PLA2G2A expression and PLA2G10 expression would be like if we were to compare Down syndrome patients with a non–Down syndrome control group." (PMID 32764374, 2020).
emphysema (1 paper, 2020). "Results showed that Nxt1 was down regulated (p < 0.05) while there was upregulation trend in Pla2g2a expression in smoker with sever emphysema patients in different level as compared to non-smoker." (PMID 32874197, 2020).
endothelial dysfunction (1 paper, 2025). In vascular diseases, endothelial dysfunction is a systemic pathological state of the endothelium (the inner lining of blood vessels) and can be broadly defined as an imbalance between vasodilating and vasoconstricting substances produced by (or acting on) the endothelium. "Dysregulation among these nodes—characterized by reduced PLA2G2A and GGT5 expression together with elevated CYP2J2 and EPHX2—may reflect a disrupted AA-EET axis that favors oxidative stress, endothelial dysfunction, and maladaptive cardiac remodeling, ultimately contributing to HF progression." (PMID 41472876, 2025).
hepatocellular adenoma (1 paper, 2023). A benign epithelial neoplasm arising from the hepatocytes. "Phospholipase A2 Group IIA (PLA2G2A), discovered by single-cell gene expression analysis, is useful for the diagnosis of hepatocellular adenoma (HCA) with conventional HCA-specific markers." (PMID 38201587, 2023).
hepatocellular carcinoma (1 paper, 2019). A malignant tumor that arises from hepatocytes. "The gene expression analysis of the IL-22-treated HepG2 cells (human hepatocellular carcinoma line) identified PLA2G2A as an upregulated antimicrobial protein in the pathogen infection study." (PMID 31461453, 2019).
hyperlipidemia (1 paper, 2022). "Especially, tryptophan and glycerophospholipid metabolism, and related targets such as TGM2, BCHE and PLA2G2A should be paid more attention, since the regulation of leonurine on these two pathways was also observed in our previous metabolomics study of clinical hyperlipidemia patients." (PMID 36072867, 2022).
Hypertension (1 paper, 2025). The presence of chronic increased pressure in the systemic arterial system. "Concurrent upregulation of PLA2 isoforms (PLA2G2A, PLA2G5) and thromboxane receptor (TBXA2R) mRNA, alongside increased thromboxane B2 (TXB2; p = 0.005), suggested that PLA2-mediated release of free F2-IsoPs contributes to placental oxidative injury and hypertension in PE." (PMID 41178997, 2025).
liver cirrhosis (1 paper, 2023). "Serum levels of PLA2G2A in patients with chronic HBV, HBV-induced liver cirrhosis, and HCC (HBV-HCC) were enhanced compared to healthy donors." (PMID 38201587, 2023).
liver diseases (1 paper, 2017). "Therefore, measuring the serum levels of PLA2G2A in HBV patients may provide a new biomarker for the diagnosis of progressive liver diseases during chronic HBV infection." (PMID 28077172, 2017).
lymph node metastasis (1 paper, 2017). "High serum PLA2G2A levels in HCC patients were associated with a lower prevalence of lymph node metastasis and a lower TNM stage." (PMID 28077172, 2017). "In the present study, we found that elevated PLA2G2A expression was associated with less frequent lymph node metastasis and lower TNM stages." (PMID 28077172, 2017). "The serum levels of PLA2G2A in HBV patients were significantly elevated and associated with disease progression, lymph node metastasis and TNM stage." (PMID 28077172, 2017).
malaria (1 paper, 2024). Malaria is a serious and sometimes fatal disease caused by a parasite that commonly infects a certain type of mosquito which feeds on humans. "For example, phospholipase A2 Group IIA (PLA2G2A) can directly kill Plasmodium via the production of toxic lipids, and overexpression of this protein enhances malaria resistance in mice." (PMID 38876107, 2024).
microangiopathic hemolytic anemia (1 paper, 2021). "Given our hypothesis that PLA2G2A is a marker of TMA and microangiopathic hemolytic anemia, we examined whether levels of PLA2G2A correlated to lowest platelet count and lowest hemoglobin during admission." (PMID 34893640, 2021).
Miscarriage (1 paper, 2025). A pregnancy that ends at a stage in which the fetus is incapable of surviving on its own, defined as the spontaneous loss of a fetus before the 22th week of pregnancy. "A stalled prepregnancy decidual reaction (PLA2G2A/DIO2 < 25th percentile) was associated with increased miscarriage risk and decreased likelihood of a live birth in a future conception cycle [odd ratio (OR), 0.52; 95% confidence interval (CI), 0.29 to 0.92, P = 0.02] (left)." (PMID 40561039, 2025).
nonalcoholic fatty liver disease (1 paper, 2023). "We analyzed other RNA-seq data in normal, nonalcoholic fatty liver disease, and steatohepatitis tissues and it indicated that PLA2G2A mRNA expression was not significantly enhanced in pathological liver tissues with the possibility of being pre-cancerous." (PMID 38201587, 2023).
osteoporosis (1 paper, 2022). A condition of reduced bone mass, with decreased cortical thickness and a decrease in the number and size of the trabeculae of cancellous bone (but normal chemical composition), resulting in increased fracture incidence. "PLA2G2A is associated with osteosarcopenia, and PLA2G2A overexpression is reported to be a valuable finding for the clinical management of sarcopenia in elderly women with osteoporosis." (PMID 35580864, 2022). "Using ML methods, we identified PLA2G2A and WRAP73 as the optimal combined biomarker set for predicting the risk of osteoporosis, and constructed a related nomogram for practical use." (PMID 35580864, 2022). "A nomogram was constructed using the gene set of PLA2G2A and WARP73, as the best combination of two genes for predicting the risk of osteoporosis." (PMID 35580864, 2022). "We therefore propose that PLA2G2A and WRAP73 may influence the development of osteoporosis by regulating bone remodeling." (PMID 35580864, 2022).
pneumonia (1 paper, 2023). An acute, acute and chronic, or chronic inflammation focally or diffusely affecting the lung parenchyma, caused by an infection in one or both of the lungs (by bacteria, viruses, fungi, or mycoplasma.). "In brief, QKL treatment probably reduced the gene (Pla2g2a, Pla2g5, and Alox12e) expression and AA levels to alleviate pneumonia." (PMID 37362920, 2023).
prostate tumor (1 paper, 2017). "PLA2G2A can stimulate tumor cell growth, whereas the product of PLA2G2A, arachidonic acid, leads to prostate tumor cell proliferation and facilitates tumor angiogenesis and metastasis." (PMID 28077172, 2017).
prune belly syndrome (1 paper, 2022). "PLA2G2A is a prominent marker of fibroblasts in the bladder, and its expression would be substantially reduced in bladder tissue from patients with prune belly syndrome." (PMID 34951074, 2022).
skin squamous cell carcinoma (1 paper, 2022). A carcinoma arising from the squamous cells of the epidermis. "Reportedly, skin-specific mouse sPLA2-IIA Tg mice (K14-Pla2g2aTGN) showed increased skin carcinogenesis, and PLA2G2A knockdown in human skin squamous cell carcinoma reduced tumorigenesity." (PMID 35076024, 2022).
tuberculosis (1 paper, 2022). A chronic, recurrent infection caused by the bacterium Mycobacterium tuberculosis. "The present study aimed to evaluate the diagnostic utility of creatine kinase-MB (CK-MB), hepcidin (HEPC), phospholipase A2 group IIA (PLa2G2A), and myosin-binding protein C (MYBPC1) for tuberculosis (TB)." (PMID 35133607, 2022).
viral infection (1 paper, 2024). "The majority of genes upregulated in HCV tumor-adjacent tissue, except IFI27, IFI6, and PLA2G2A, show average expression below 1 TPM in GTEx normal liver samples, suggesting that the upregulation of these immune-related genes in HCV tumor-adjacent tissue is likely mediated by the viral infection." (PMID 39005337, 2024).
tumor (65 papers, 2004 to 2026). "This would suggest that both tumor-associated PLA2G2A as well as ascites-associated PLA2G7 may be useful theranostic candidates." (PMID 33391540, 2021). "This intra-patient heterogeneity was replicated with Chromium data where we annotated two tumor subclusters for Tu_B3 corresponding to the area A and B with specific DE genes PLA2G2A and NPPC correspondingly." (PMID 40355415, 2025). "Some studies have also reported that HMOX1, SST, PLA2G2A, KRT4 and COL3A1 are associated with tumor progression and prognosis." (PMID 38461430, 2024). "PLA2G2A expression is negatively correlated with infiltration depth, lymph node metastasis, and the tumor-lymph node-metastasis stage." (PMID 39267107, 2024). "Conversely, PLA2G2A functions as a tumor suppressor in CCA by inhibiting cell proliferation, invasion and migration." (PMID 39267107, 2024). "Immunohistochemistry using the PLA2G2A antibody in these tissues indicated that the positive reaction was mainly observed in hepatocytes of I-HCAs and stromal cells surrounding the tumor tissue in HCC were also stained." (PMID 38201587, 2023). "Tumor multiplicity and incidence over time were delayed in Pla2g2a–/– mice relative to Pla2g2a+/+ mice, although the volume of the tumors, once they had developed, was similar between the genotypes." (PMID 35076024, 2022). "We also confirmed that PLA2G2A, identified as an upregulated gene in the tumor and directly regulated by AR in network #3, to be inhibited by DHT treatments in the cultured LNCaP cells." (PMID 33808801, 2021). "H&E staining was first used to distinguish tumor stroma, and then IF staining was used to detect PLA2G2A expression." (PMID 34035226, 2021). "Phospholipase A2 Group IIA (PLA2G2A), especially the secretory form, is overexpressed in almost all human PCa specimens and correlate with high tumor grade." (PMID 34386430, 2021). "As reported in the present study, PLA2G2A showed the highest variance of expression in tumor tissue from different patients and reached the highest expression level among all PLA2 isoforms in a subset of patients." (PMID 33391540, 2021). "Pla2g2a (found at the same region as Mom1) has also been shown to affect the net growth rate of adjacent tumours." (PMID 28331556, 2017). "The involvement of PLA2G2A in tumor progression in humans has been demonstrated to be dualistic." (PMID 39267107, 2024). "Interestingly, PLA2G2A plays a stem cell regulator role in the intestinal crypt and is found at a high level in the tumour microenvironment, stimulating cancer progression and metastasis." (PMID 39768140, 2024). "Some genes function as tumor suppressor including PLA2G2A, PI3, and NOS2." (PMID 36944972, 2023). "One possibility is the oncogenic transformation of PLA2G2A-positive I-HCAs in this tumor tissue." (PMID 38201587, 2023). "Therefore, PLA2G2A likely served a stage-dependent role, more actively engaged in early carcinogenesis than in tumor progression." (PMID 36198671, 2022). "Also, it was confirmed that PLA2G2A and new tumor event after initial treatment were statistically significant prognostic value with multivariable analysis (PLA2G2A: HR = 1.8, p = 0.04 and new tumor event after initial treatment: HR = 2.1, p = 0.01)." (PMID 33717076, 2021). "It has been suggested that the anti-bacterial activity of Pla2g2a is involved in tumor inhibition." (PMID 33408272, 2020). "Because of its localization within the Mom-1 (Min modifier) locus, and its promotion of tumors in APCMin mice, it had first been suggested that PLA2G2A may represent a tumor suppressor gene involved in familial forms of CRC." (PMID 18992148, 2008). "Furthermore, in our single-cell dataset, PLA2G2A+ CAFs were observed to interact with various immune cells, especially macrophages, which suggests that PLA2G2A+ CAFs may be a factor in tumor immune infiltration, promoting tumorigenesis and tumor development." (PMID 36357424, 2022).
tumor (continued). "By intersecting these genes, we identified three genes (PLA2G2A, DPEP1, and G0S2) that were upregulated in primary and recurrent tumor tissue." (PMID 40519301, 2025). "Conversely, we observed a significant downregulation of tumor-suppressive transcriptional regulators such as CPEB1, CDH15, GFPT2, and PLA2G2A." (PMID 40950184, 2025). "For instance, PLA2G2A+ CAFs can regulate tumorigenesis by modulating tumor metabolism, while CD63+ CAFs strengthen the drug tolerance of tumor cells." (PMID 40855046, 2025). "In further in vivo assays, downregulation of PLA2G2A promoted the growth of CCA cell xenograft tumors, whereas overexpression of PLA2G2A inhibited CCA cell xenograft tumor growth." (PMID 39267107, 2024). "PLA2G2A overexpression potentiated proliferation, inhibited apoptosis, and significantly facilitated stemness of GBC cells, whereas unexpectedly retarding tumor migration and invasion." (PMID 36198671, 2022). "Among the genes upregulated in the atypical tumor compared to the nevus were: SOX10, the receptor tyrosine kinases ROS1 and NTRK3, PLA2G2A, and HOXA11, while DUSP2, PDGFD, and ELN were downregulated." (PMID 35052351, 2021). "Therefore, as a tumor suppressor in CCA cells, PLA2G2A restrains proliferation, invasion, and migration." (PMID 39267107, 2024). "In the NBNC-HCC specimens, PLA2G2A was stained non-specifically in the center of the tumor owing to necrosis (black arrows)." (PMID 38201587, 2023). "Within the tumor population, we identified expression of phospholipase enzymes PLA2G2A and PLA2G4A and PTGS2 (COX2), but not PTGS1 (COX1)." (PMID 36277993, 2022). "Therefore, PLA2G2A+ CAFs may be recruited and dominated by HER2+ tumor cells to migrate or differentiate in the process of tumor development." (PMID 36357424, 2022). "No variation in expression between the tumours and normal mucosa was observed for PLA2G1B, PLA2G2A, PLA2G2F, PLA2G10, PLA2G12A and PLA2G12B and for the M-type sPLA2 receptor (PLA2R1)." (PMID 18212756, 2008). "However, despite the presence of significantly expressed ligand–receptor pairs in tumor cells, CAF1, and CAF2 cells (e.g., GRN/SORT1, PLA2G2A/a5b1 complex), there is a lack of spatial proximity between CAF1 and CAF2 cells." (PMID 38229179, 2024).